RNU6-1339P (RNA, U6 small nuclear 1339, pseudogene)
Gene: Small nuclear RNA gene on chromosome 15 (83,824,863 to 83,824,953, reverse strand). Ensembl gene ENSG00000200444.
Homologues: Orthologues: chimpanzee U6 (99% identical), chimpanzee U6 (93% identical), rabbit U6 (78% identical), pig U6 (70% identical), mouse Gm56200 (58% identical). Paralogues in human: RNU6-1152P (82% identical), RNU6-196P (82% identical), RNU6-211P (81% identical), RNU6-116P (80% identical), RNU6-30P (79% identical), RNU6-732P (79% identical), RNU6-820P (79% identical), RNU6-1075P (78% identical), RNU6-15P (78% identical), RNU6-16P (78% identical), RNU6-25P (78% identical), RNU6-29P (78% identical), and 1280 more.